APOE (apolipoprotein E)
Diseases named in the same sentence as APOE in open-access papers (continued):
Sharing a sentence is not in itself a finding about the gene and the disease.
tumor (continued). "Subsequently, four groups of mouse tumor specimens underwent Hematoxylin‐eosin (H&E), ki67 IHC, and mIHC staining to investigate tumor proliferation potential and the relationship between APOE+ macrophages and CD8+ Tex cells." (PMID 38569519, 2024). "Both CD14+APOE+ cells and MMP7+ tumour cells were associated with poorer survival outcomes and immunotherapy therapy response, underscoring their potential as therapeutic targets." (PMID 39187937, 2024). "To further explore the function of APOE, we established in vivo tumour models by injecting TRAMPC‐2 PCa cell lines into C57BL/6 mice (WT or Apoe‐KO), and found that the tumours in the Apoe‐KO group were relatively smaller." (PMID 39138838, 2024). "reviewed ApoE (and potentially other apolipoproteins)-mediated lipid antigen transport, revealing its critical role in tumor immune surveillance and offering new perspectives for immunotherapy and vaccines (Schümann and De Libero, 2006)." (PMID 38524185, 2024). "This difference in findings suggests that, in addition to APOE’s role in ferroptosis and tumor modulation, the function of APOE-rs429358 specifically includes modulating hormonal balance in female PTC patients." (PMID 38067270, 2023). "This is consistent with previous studies that showed that APOE mediates poor outcomes in tumor patients." (PMID 37318594, 2023). "We found that the proportion of Macro_APOE/CTSZ was significantly higher in tumor than normal tissues and accounted for more than 20% of macrophages in most CRC patients." (PMID 36587392, 2023). "Whole-body LDIR on metastatic mouse models induced anti-tumor responses via alterations of the immunosuppressive tumor environment, leading to a reduction of pro-inflammatory Ly6chigh monocytes in APOE−/−mice." (PMID 37511215, 2023). "In order to figure out the underlying causes that Macro_APOE/CTSZ specifically upregulated glutamate transport and glutamate‐to‐glutamine metabolic pathway, we analyzed the glutamate‐related metabolic genes in tumor cells." (PMID 36587392, 2023). "Further patterns have also been identified, like APOE levels being significantly higher when a tumor has metastasized to the liver." (PMID 38067270, 2023). "Nano-reshaper impressively inhibited rapid tumor growth compared to 5% Glu group, as proved by the lower tumorous luciferase intensity, while either ApoE-CaCP or ApoE-pLIGHT@CaP showed a partial inhibitory effect." (PMID 36702831, 2023). "In particular, we uncovered a tumor‐associated macrophage (TAM) subpopulation, APOE+CTSZ+TAM, that was present in high proportions in tumor samples and exhibited immunosuppressive characteristics through upregulating the expression of anti‐inflammatory genes." (PMID 36587392, 2023). "In intracranial murine GBM model, we found ApoE accumulation in the GBM tumor tissue margin, which was significantly higher than in adjacent tissue." (PMID 37474548, 2023). "Conversely, tumors evolved from ApoE knockout (ApoE−/−) mice have reduced cancer growth, lowered tumor burden, lessened fibrosis, and fewer immune-suppressive cells (Treg and MDSC), while also having increased cytotoxic CD8+ T lymphocyte infiltration." (PMID 37444617, 2023). "APOC1 +APOE+ TAMs promote distant metastasis of ESCC by aiding tumor colonization in the lymph nodes through matrix reorganization, collagen deposition, and MEM." (PMID 37664173, 2023). "Compared with primary tumor, higher abundance of APOC1+APOE+ macrophages were observed in tumor nest of metastatic lymph node." (PMID 36709495, 2023). "Tumor-bearing mice intravenously injected with the ApoE–liposomes loaded with pcDNA3.1-pSurvivin-TK, and later treated with ganciclovir, had a significantly longer survival period in comparison to the control groups." (PMID 36986734, 2023). "Glutaminase (GLS), converting glutamine to glutamate, was downregulated in tumor cells compared with Macro_APOE/CTSZ, in CRC samples." (PMID 36587392, 2023).
tumor (continued). "CXCL1 expression in cancer cells can be increased by IL-17 and also apolipoprotein E (ApoE) secreted by inflammatory CAF into the tumor microenvironment." (PMID 37408240, 2023). "In a study examining CAFs in short-term versus long-term OC survivors, the APOE(CAFs) - LRP5(tumor) interaction pattern between CAFs and tumor cells at the tumor-stroma interface was associated with short-term survival." (PMID 38164130, 2023). "In recent years, abnormally high expression of apoE has been detected in the serum and tumor tissues of CRC patients." (PMID 37310025, 2023). "In a recent study using a preclinical tumor model, researchers discovered that sEVs derived from M2 macrophages downregulated tumor cell MHC-I expression through the delivery of apolipoprotein E (ApoE)." (PMID 38093355, 2023). "Gene set enrichment analysis (GSEA) elucidated that the treatment of tumor cells with recombinant ApoE upregulates NF-κB signaling, which in turn augments the expression of CXCL1 and CXCL5 acting as chemoattractants for immune-repressive myeloid cells." (PMID 37444617, 2023). "Using matrix-assisted laser desorption/ionization mass spectrometry imaging (MALDI-MSI), it was found that in MTC, APOE was expressed within the tumor’s amyloid components." (PMID 38067270, 2023). "The serum levels of apoE in these tumor-baring apoE-/- mice increased progressively and considerably with tumor growth." (PMID 36341364, 2022). "This study’s results show that the total protein level of APOE and the phosphorylation level of APOE at the S147 site in the primary tumor were higher than in the normal control group." (PMID 37304007, 2022). "TAMs were present in both tumor and metastatic lymph nodes and were defined based on the shared expression of APOE, APOC1, and C1QA-C, and the mutually exclusive expression of TREM2/CADM1 and FOLR2." (PMID 35746551, 2022). "In the mouse model, apoE appears to be an immune modulator critical for enabling tumor cell growth through suppression of immune activation." (PMID 36341364, 2022). "CD28 was also upregulated in the tumor from the apoE-/- mice in which wt tumor cells were inoculated (wt/apoE-/-)." (PMID 36341364, 2022). "Binary logistic regression was performed to evaluate the influence of ApoE on the development of LSCC with different tumor sizes." (PMID 35892323, 2022). "We analyzed the distributions of ApoE genotypes and allele frequencies in the control group and patients with LSCC subgroups according to the tumor differentiation grades." (PMID 35892323, 2022). "Of note, MKI67 monocytes and APOE macrophages were mainly derived from tumor, while ADAP2 and MARCO macrophages were mainly from ascites." (PMID 36248860, 2022). "Our studies show that tumor cells depleted of apoE can stimulate remarkable immune activation in co-culture experiments." (PMID 36341364, 2022). "APOE level was significantly correlated with tumor-infiltrating cells (B cells, CD8+ T cells, neutrophils, and dendritic) and immune biomarkers in PTC." (PMID 35371313, 2022). "Activation of ApoE restricted the innate immune system’s suppression of cancer cell proliferation, thus promoting tumor growth and metastasis in many types of cancers." (PMID 35892323, 2022). "The findings of the current study showed that the APOE expression was significantly upregulated and positively correlated with tumor size ≥2 cm and extrathyroidal invasion." (PMID 35090515, 2022). "Specifically, ApoE can promote cancer cell proliferation and tumor metastasis in patients with lung ADC and thereby it acts as a potential biomarker for predicting lung ADC progression." (PMID 36506554, 2022). "This revealed tumor-macrophage interactions via APOE-TYROBP (DAP12) as the strongest interaction among tumor microenvironment interactions." (PMID 36028490, 2022).
tumor (continued). "To evaluate if the protective effect against tumor growth with apoE targeting is immune mediated, we harvested the first 3 mice from each group that grew tumors to 15mm for tumor immune profiling." (PMID 36341364, 2022). "For this reason, APOE is likely to be targeted for modifying tumor macrophage infiltrate and augmenting checkpoint immunotherapy." (PMID 36147474, 2022). "ApoE promoted anti-tumor immunity by targeting infiltrating innate myeloid derived suppressor cells (MDSC) via Liver X receptor (LXR) agonism." (PMID 36341364, 2022). "It is found that an increased level of serum ApoE in NSCLC patients is involved in tumor node metastasis (TNM) stages, lymph node invasion and metastasis." (PMID 36506554, 2022). "The later stages of tumor progression tend to have higher expression levels of APOE, except for THCA." (PMID 37304007, 2022). "Camouflaging the nanogels with apolipoprotein E peptide-decorated erythrocyte membrane further allows prolonged blood circulation and active tumor targeting." (PMID 36369424, 2022). "Our results also add to a conflicted literature in which apoE can mediate either pro- or anti-tumor effects." (PMID 36341364, 2022). "We found that myeloid cells from two clusters (aMΦ, bMΦ), characterized by the expression of tumor-associated macrophage genes (CD163, CCL4, APOE, and HLA-DRA) were strongly connected to the CD8+ exhausted and CD4+ Th1 T cell clusters." (PMID 35177622, 2022). "ApoE inhibits activation of immune cells, inflammatory signals, and tumor immunogenicity both locally and systemically via cellular secretion and host production." (PMID 36341364, 2022). "One study shows that in MDA-MB-231 cells, the expression of ApoE or ApoA1 inhibit the growth and migration of tumor cells via preventing EMT, probably through preventing the de novo production of fatty acids and cholesterol entry into BC cells." (PMID 36506554, 2022). "From the cell ratio, it can be seen that Monocytes_IGHG3 is only present in cancer tissues, Monocytes_APOE is also abundant in tumor tissues, and Monocytes_STMN1 is more distributed in healthy tissues." (PMID 36569220, 2022). "The unique apolipoprotein that seems to be involved in GBM disease is the Apolipoprotein E (APOE), which promotes tumor growth and metastasis by inhibiting the immune system." (PMID 35216175, 2022). "Both the expression of apoE as well as the secretion of apoE from the tumor cells seems to have clear immunosuppressive effects." (PMID 36341364, 2022). "The decoration with ApoE-peptide functionalized erythrocyte membrane further extends the circulation time, improves tumor accumulation, and facilitates the BBB penetration of the nanogels." (PMID 36369424, 2022). "The results reveal a critical role for tumor secreted apoE as a comprehensive checkpoint which appears to alter dendritic cell function and inhibit T-cell efficacy." (PMID 36341364, 2022). "The suppressive effect observed on tumor growth in vivo with apoE suppression appears indirect as apoE KO cells proliferate normally." (PMID 36341364, 2022). "In the hypercholesterolemic ApoE KO-mice and other mouse models, a high-fat/high cholesterol diet enhanced tumour growth and metastasis." (PMID 35022465, 2022). "There is some scientific evidence that ApoE affects tumor development, including head and neck tumors." (PMID 35892323, 2022). "Analysis of the relationship between APOE expression and its clinicopathological features, showed that expression of APOE was significantly positively correlated with tumor size (p = 0.005) and extrathyroidal invasion (p = 0.028)." (PMID 35090515, 2022). "Genome-wide ligand-receptor analysis revealed APOE-TYROBP as the strongest tumor microenvironment interaction, suggesting a regulatory axis from tumor cells to suppressive TAMs." (PMID 36028490, 2022). "LXR also stimulates the secretion of APOE from macrophages and other stromal cells to inhibit tumor growth, angiogenesis, or metastasis." (PMID 38089448, 2022).
tumor (continued). "The endocytosis of multiple extracellular ligands of LRP1, including apolipoprotein E (ApoE)- and lipoprotein lipase-enriched lipoproteins, thrombospondin, and plasminogen activators, is important in vascular biology and tumor progression." (PMID 34124208, 2021). "APOE, APOC1, and SPP1 were highly expressed in tumor-associated macrophages resulting in anti-inflammatory macrophage phenotypes." (PMID 34697289, 2021). "This approach allowed the successful visualization of macrophage migration into the tumor sites and atherosclerotic plaques in tumor-bearing and ApoE-/− mouse models, respectively." (PMID 34371758, 2021). "Macro_C1QA also expressed a set of genes found previously in tumor-associated macrophages, including C1QA, APOE, and C1QB, resembling the signature of M2 phenotype." (PMID 34566966, 2021). "APOE regulates lipid homeostasis in the systemic circulation and induces inflammatory immune responses in the tumor microenvironment." (PMID 33384961, 2020). "ApoE impedes tumor invasion and endothelial cell recruitment, but liver-X receptors (LXRs) inhibit ApoE expression." (PMID 32942545, 2020). "Our previous studies demonstrated that apoA-I, apoJ and apoE mimetic peptides inhibit tumor development in mouse models of ovarian and colon cancer, and play an important anti-atherogenic role in facilitating the clearance of LDL from the circulation." (PMID 32462055, 2020). "In 2015, another analysis demonstrated that the posttranslational modifications of apoE, such as methylation and dihydroxylation, play roles in tumor development." (PMID 32306242, 2020). "ApoE is differentially expressed in EOC versus serous borderline tumors and normal ovarian surface epithelium, implicating apoE as a potential tumor-associated marker in EOC." (PMID 32462055, 2020). "We show that expressing apoA-I or apoE stimulates proliferation, migration, and tumor growth of MCF-7 cells." (PMID 32321558, 2020). "In lung and ovarian carcinomas, apoE is a promoter for the growth and migration of tumor cells, but in melanoma, it is an inhibitory factor for angiogenesis and metastasis." (PMID 32306242, 2020). "The inhibitory effects of ApoE KO on tumor growth and metastasis were associated with an increased number of infiltrated immune cells, CD57+ NK cells, and TREM-1 expression at tumor tissues." (PMID 31275318, 2019). "Specifically, better preservation of the ApoE coating can be found in the nanospheres that are still circulating in the blood and that accumulate in the tumor." (PMID 31586045, 2019). "The histological analysis showed that the tumor size in ApoE KO mice were significantly smaller compared than WT mice." (PMID 31275318, 2019). "All these findings pointed out that prior coating with ApoE helps maintain a corona rich in dysopsonins, which eventually endow the nanomaterials with enhanced enrichment in tumor tissue." (PMID 31586045, 2019). "The phosphorylation of p38 and STAT3 was also decreased in tumor tissues of ApoE KO mice compared to those of WT mice." (PMID 31275318, 2019). "Western blot data showed that the protein levels of PCNA, CDK4, CDK6, Cyclin D1, MMP-2, MMP-9, and Bcl-2 were decreased, but cleaved caspase-3 was increased in tumor tissues of ApoE KO mice compared to those of WT mice." (PMID 31275318, 2019). "ApoE–/– mice exhibited increased tumor growth and displayed a greater number of spontaneous metastases to the lungs." (PMID 31208017, 2019). "The Gd-labeled G-half/all-OH samples were passivated with IgE/ApoE before injection into tumor-bearing mice through the tail vein." (PMID 31586045, 2019). "Serum ApoE levels were elevated in NSCLC patients compared with normal controls, and were associated with tumor stages." (PMID 31275318, 2019). "A recent study showed that ApoE regulates MDSCs survival and tumor progression; ApoE−/− mice had increased levels of PMN-MDSCs and M-MDSCs." (PMID 31275326, 2019).
tumor (continued). "Hematoxylin and eosin (H&E) staining showed that the sizes of tumor lesion at two weeks were significantly larger in ApoE−/− mice." (PMID 29458390, 2018). "In our model, immunofluorescence analysis at the early stage of the tumor establishment showed significantly increased FAK activation in the tumor cells from ApoE−/− mice compared to WT controls." (PMID 29458390, 2018). "The alternative of ApoE after neoadjuvant chemotherapy cannot reflect the real expression level in the tumor." (PMID 30631342, 2018). "More importantly, our results demonstrated that PD-325901 treatment significantly delayed the tumor progression in ApoE−/− mice compared to PBS-treated mice." (PMID 29458390, 2018). "By anatomy and quantification, morbid ApoE−/− mice displayed a heavier tumor burden compared to WT control." (PMID 29458390, 2018). "Our results confirmed the markedly elevated expression of MMP-10 and MMP-9 in the tumor lesions of ApoE−/− mice compared to that in WT mice." (PMID 29458390, 2018). "First, tumor-infiltrating M2 macrophages express significantly higher levels of ApoE and transfer functional ApoE exosomes to neighboring GC cells." (PMID 29567987, 2018). "BAPN treatment was initiated in 20-week-old ApoE−/− mice and sustained for one month prior to tumor establishment." (PMID 29458390, 2018). "In this study, we found that the ApoE expression was higher in the primary tumor of liver metastasis as compared with the stage II." (PMID 30631342, 2018). "Two cohorts of CRC patients were classified into low ApoE expression group (SI 0–4) and high ApoE expression group (SI 6–12) based on the immunohistochemistry staining of the primary tumor." (PMID 30631342, 2018). "Thesuccessful self-assembly with ApoE is of vital importance for tumour targeting,because it can enable the recognition of the nanostructure by the hungry cancercells, which absorbed nutrient by macropinocytosis." (PMID 28489075, 2017). "Apolipoprotein E3: It is involved in inhibiting the proliferation of tumor cells and endothelial cells among other cell types in a dose and time dependent manner." (PMID 27875990, 2016). "In particular, high apoE expression was correlated with deeper tumor invasion or more positive lymph node metastasis, contributing to shorter survival." (PMID 26817942, 2016). "Nevertheless, APOE is known to be involved in signal transductions that are important in tumor cell survival, proliferation and migration." (PMID 22606345, 2012). "We examined in B16 tumour-bearing mice the tumour-localizing properties of apoE liposomes and the disposition of an incorporated lipophilic derivative of daunorubicin (LAD)." (PMID 9862571, 1998). "We conclude that apoE liposomes enable LDL receptor-mediated specific delivery of antineoplastic (pro)drugs to tumours, and, therefore, constitute an attractive novel option for anti-tumour chemotherapy." (PMID 9862571, 1998). "In this study, we have shown that APOE secreted by astrocytes accumulated at the tumor edge." (PMID 40745073, 2026). "Despite the significant increase in APOE in the tumor core astrocytes, their small number suggests that the accumulated APOE seen in the ALTS1C1 tumor core may originate from other cells." (PMID 40745073, 2026). "Similarly, the GL261 model showed more APOE signal in tumor edge (12.0 ± 9.5%) than peritumoral normal tissue (4.0 ± 3.3%)." (PMID 40745073, 2026). "First, astrocytes could contribute to lipid delivery by secreting APOE, which facilitates lipid transport to tumor cells." (PMID 40745073, 2026). "The observation that both APOE and cholesterol accumulate primarily in the tumor-surrounding tissue is consistent with our previous finding that the tumor edge exhibits unique characteristics, including higher microvascular density (MVD) and better vessel function, but expresses more CAIX." (PMID 40745073, 2026). "The localized pattern of APOE RNA supports the idea that only a subset of cells may be actively expressing APOE in the tumor core." (PMID 40745073, 2026).